GSDMB (gasdermin B)
Description:
[Gasdermin-B]: Precursor of a pore-forming protein that acts as a downstream mediator of granzyme-mediated cell death. This form constitutes the precursor of the pore-forming protein: upon cleavage, the released N-terminal moiety (Gasdermin-B, N-terminal) binds to membranes and forms pores, triggering pyroptosis. Also acts as a regulator of epithelial cell repair independently of programmed cell death: translocates to the plasma membrane and promotes epithelial maintenance and repair by regulating PTK2/FAK-mediated phosphorylation of PDGFA. [Gasdermin-B, N-terminal]: Pore-forming protein produced by cleavage by granzyme A (GZMA), which causes membrane permeabilization and pyroptosis in target cells of cytotoxic T and natural killer (NK) cells. Key downstream mediator of granzyme-mediated cell death: (1) granzyme A (GZMA), delivered to target cells from cytotoxic T- and NK-cells, (2) specifically cleaves Gasdermin-B to generate this form. After cleavage, moves to the plasma membrane, homooligomerizes within the membrane and forms pores of 10-15 nanometers (nm) of inner diameter, triggering pyroptosis. The different isoforms recognize and bind different phospholipids on membranes, promoting cell death of different target cells. [Isoform 4]: Precursor of a pore-forming protein that acts as a downstream mediator of granzyme-mediated cell death and mediates pyroptosis. Following cleavage and activation by granzyme A (GZMA), the N-terminal part binds to membrane inner leaflet lipids, homooligomerizes within the human plasma membrane and forms pores of 10-15 nanometers (nm) of inner diameter, triggering pyroptosis. Recognizes and binds membrane inner leaflet lipids of human cells, such as phosphatidylinositol 4-phosphate, phosphatidylinositol 5-phosphate, bisphosphorylated phosphatidylinositols, such as phosphatidylinositol (4,5)-bisphosphate, and more weakly to phosphatidic acid. Also binds sufatide, a component of the apical membrane of epithelial cells. [Isoform 6]: Precursor of a pore-forming protein that acts as a downstream mediator of granzyme-mediated cell death and mediates pyroptosis of human cells. Following cleavage and activation by granzyme A (GZMA), the N-terminal part binds to membrane inner leaflet lipids, homooligomerizes within the human plasma membrane and forms pores of 10-15 nanometers (nm) of inner diameter, triggering pyroptosis. [Isoform 1]: Precursor of a pore-forming protein that acts as a downstream mediator of granzyme-mediated cell death and specifically mediates cell death of Gram-negative bacteria in response to infection. Following cleavage and activation by granzyme A (GZMA), the N-terminal part recognizes and binds phospholipids found on Gram-negative bacterial membranes, such as lipid A and cariolipin, homooligomerizes within the bacterial membranes and forms pores, triggering pyroptosis followed by cell death. In contrast to isoform 4, does not bind to membrane inner leaflet lipids of host human cell, such as phosphatidylinositol 4-phosphate, phosphatidylinositol 5-phosphate, bisphosphorylated phosphatidylinositols, such as phosphatidylinositol (4,5)-bisphosphate. [Isoform 2]: Not able to trigger pyroptosis. [Isoform 3]: Not able to trigger pyroptosis.
Synonyms: GSDML; PP4052; PRO2521; GSDMB-1
Tractability: Antibody: UniProt places it where antibodies can reach, with high confidence; its Gene Ontology location is reachable by antibodies, with high confidence; UniProt predicts a signal peptide or a membrane-spanning region. PROTAC: UniProt records ubiquitination sites on it; ubiquitination databases record sites on it.
Gene: Protein-coding gene on chromosome 17 (39,904,595 to 39,919,854, reverse strand). Ensembl gene ENSG00000073605.
Subcellular location: Cytoplasm (Gasdermin-B); Cell membrane (Gasdermin-B, N-terminal)
Subcellular location (Human Protein Atlas): Nucleoplasm; Cytosol
Gene Ontology:
Molecular function: phosphatidylinositol-4,5-bisphosphate binding; phosphatidylinositol-4-phosphate binding; phosphatidylserine binding
Biological process: defense response to bacterium; pyroptotic inflammatory response
Cellular component: cytoplasm; cytosol; plasma membrane
Genetic constraint (gnomAD): Loss-of-function variants: 21 observed, 29.36 expected, observed/expected ratio (o/e) 0.72, 90% interval 0.51 to 1.03. The upper end of that interval is the gene's LOEUF score, 1.03, which puts it in group 4 of 6, group 1 being the genes least tolerant of losing a copy. Missense variants: 380 observed, 425.16 expected, observed/expected ratio (o/e) 0.89, 90% interval 0.82 to 0.97. Synonymous variants: 146 observed, 168.34 expected, observed/expected ratio (o/e) 0.87, 90% interval 0.76 to 1.
Homologues: Orthologues: chimpanzee GSDMB (99% identical), pig GSDMB (56% identical), zebrafish pjvk (13% identical). Paralogues in human: GSDMA (29% identical), GSDMD (26% identical), GSDMC (21% identical), PJVK (13% identical).
Diseases named in the same sentence as GSDMB in open-access papers:
GSDMB is named in the same sentence as 114 diseases in open-access papers, as found by Europe PMC text mining. Sharing a sentence is not in itself a finding about the gene and the disease. The quoted sentences say what the papers report.
asthma (158 papers, 2009 to 2026). "Another focus of the GSDMB rs7216389 polymorphism is its association with the early onset of asthma, which suggests that this sequence variant increases the risk of developing asthma symptoms earlier in life." (PMID 39906448, 2025). "Variations in the rs7216389 polymorphism of GSDMB can influence its expression, potentially altering immune cell function and contributing to asthma pathogenesis." (PMID 39906448, 2025). "With notable differences in the frequency of the rs7216389 variant between populations, ancestry also shapes the impact of GSDMB polymorphisms on asthma susceptibility." (PMID 39906448, 2025). "Studies show that carriers of the asthma-associated risk allele at 17q21 exhibit increased expression of the corresponding SNP, especially in genes such as GSDMB and ORMDL3." (PMID 40867500, 2025). "Another eQTL fine‐mapping analysis of the 17q12‐21‐haploblock region showed that GSDMB was the leading candidate gene for asthma susceptibility in both African Americans and European Americans." (PMID 40133993, 2025). "Significant genotyping evidence for the GSDMB gene polymorphism rs7216389 indicates a substantial correlation between the SNP variant and asthma condition (p < 0.001), which is corroborated by the likelihood ratio test chi-square 277.259." (PMID 39906448, 2025). "Among the various epigenetic mechanisms, DNA methylation modifications are the most robustly supported by pediatric studies, particularly those implicating ORMDL3 and GSDMB in asthma susceptibility and inflammation." (PMID 40806756, 2025). "Like ZPBP2 that was identified in our GWAS of children's own genotypes and childhood asthma, GSDMB also lies within the same core region on 17q12‐q21 that is strongly linked to childhood‐onset asthma." (PMID 40133993, 2025). "Higher expression levels of GSDMB associated with asthma and increased GSDMB expression further affected genes involved in interferon signaling, major histocompatibility complex class I antigen presentation, and immune pathways." (PMID 39299705, 2024). "GSDMB expression is increased in sepsis and Crohn’s disease, whereas GSDMB polymorphism is associated with asthma." (PMID 38711020, 2024). "The specific object of attention in the present study was a polymorphism within the GSDMB gene, and more particularly in the region of rs7216389, which was found to have an extremely strong link to asthma." (PMID 40104184, 2024). "Single nucleotide polymorphisms in GSDMB display a strong correlation with GSDMB expression levels and the severity of asthma." (PMID 38225586, 2024). "GSDMB locus variants were previously associated with asthma, cardiovascular disease, and neutrophil counts in the GWAS Catalog." (PMID 39299705, 2024). "The lead variants of the CDHR3 and GSDMB loci showed significant associations with asthma and respiratory system–related phenotypes, assayed among the traits in the FinnGen DF10." (PMID 39299705, 2024). "In GWASs, it was also discovered that there was a substantial correlation between asthma and GSDMB polymorphisms." (PMID 40104184, 2024). "In summary, we discovered a novel role for GSDMB, a genetic risk factor for asthma associated with 17q21 locus in regulating mtDNA-induced innate immune response in respiratory epithelial cells." (PMID 38737375, 2024). "A case-control association study conducted in the Japanese population observed that ORMDL3/GSDMB is an important susceptibility gene for early-onset adult asthma." (PMID 38562155, 2024). "A splice variant (rs11078928) in GSDMB skips an essential exon from the transcript, affects the induction of pyroptosis, and reduces the risk of asthma." (PMID 38711020, 2024). "CDHR3 and GSDMB loci were associated with asthma in previous studies and the pheWAS, and the GSDMB locus in the long arm of chromosome 17 (17q) is the strongest known asthma risk locus." (PMID 39299705, 2024).
asthma (continued). "This review provides an overview of genetic and pathological mechanisms associated with childhood asthma, focusing on the Gasdermin B (GSDMB) gene variant rs7216389." (PMID 40104184, 2024). "Our cFDR analysis also elevated to genome-wide significance the SNP rs4795400, located in an intron of GSDMB and strongly associated with childhood-onset asthma." (PMID 39241920, 2024). "Polymorphisms of GSDMB have been linked to some chronic inflammatory diseases in the respiratory tract, such as asthma." (PMID 38225586, 2024). "In our study, we found that GSDMB, the asthma risk gene located in the 17q21, promotes the activation of mtDNA-induced cGAS-STING pathway via facilitating the translocation of STING into Golgi and subsequent interaction with TBK1." (PMID 38737375, 2024). "Risk alleles in these 17q21 SNPs are associated with asthma severity and exacerbation and increased expression of the gasdermin B (GSDMB) gene in airway epithelial cells." (PMID 38737375, 2024). "Single nucleotide polymorphisms in GSDMB have been found to be associated with higher GSDMB expression which translates into asthma severity and a higher number of disease exacerbations." (PMID 38693919, 2024). "In recent years, many studies have identified that GSDMB seems to play an important role in asthma susceptibility and severity." (PMID 38225586, 2024). "We obtained 24 iQTLs associated with this loop, all of them being significant nCD4 eQTLs of GSDMB and 21 of them (like the SNPs rs2305479, rs7216389) are nCD4 eQTLs for the asthma risk associated gene ORMDL3." (PMID 39289357, 2024). "Considering the association between psoriasis, IBD, and asthma, as well as documented engagement of GSDMB in IBD and asthma pathology, we found it interesting to study this gasdermin in psoriatics." (PMID 38693919, 2024). "Genome-wide association studies have demonstrated a close correlation between GSDMB polymorphisms and susceptibility to asthma, IBD, and other chronic inflammatory diseases." (PMID 37781519, 2023). "Single nucleotide polymorphisms in GSDMB associated with asthma severity, exacerbations, and GSDMB expression levels." (PMID 36911417, 2023). "Genome-wide association studies (GWAS) in recent years have shown that polymorphisms of the GSDMA and GSDMB genes are closely related to the occurrence of asthma." (PMID 37250902, 2023). "The childhood-onset asthma–associated alleles at a missense SNP in GSDMB, rs2305480-G, had an estimated OR for childhood-onset asthma of 1.17 (CI 1.05, 1.30) in a meta-analysis of 3904 African American subjects." (PMID 36175932, 2022). "While another study found that the levels of GSDMB were increased remarkably in patients with asthma, and were associated with the severity of asthma." (PMID 35720396, 2022). "The upregulated expression of GSDMB in bronchial epithelial cells was also found to increase the susceptibility to asthma." (PMID 36248872, 2022). "Genome-wide association studies (GWAS) uncovered a strong correlation between GSDMB and susceptibility to inflammatory diseases including Crohn’s disease, asthma, and type I diabetes." (PMID 35795683, 2022). "GSDMA is expressed in epithelial cells and has been linked to autoimmune diseases and cancer.GSDMB is reported to be associated with asthma and colitis." (PMID 35634294, 2022). "Marinho, Custovic supported the association of both genes to adult asthma, while Qiu, Zhao and Wan, Shrine only supported the relationship in GSDMB." (PMID 36201519, 2022). "In another large-scale genome-wide analysis of asthma, mutations in the GSDMB gene were associated with childhood asthma and autoimmune diseases." (PMID 35647057, 2022). "Where one minor allele in the GSDMB gene is sufficient to induce significant changes in the IgE serum levels and plays a role in the pathogenesis of asthma in asthmatic children of the Jordanian population." (PMID 36201519, 2022).
asthma (continued). "We and others have recently shown that risk for asthma conferred by variation at the 17q12-q21 locus was due to these SNPs, implicating GSDMB function and/or expression in airway epithelial cells in asthma pathogenesis." (PMID 36175932, 2022). "Gasdermin A (GSDMA) and gasdermin B (GSDMB) have been associated with childhood and adult asthma in many populations including the Jordanian population." (PMID 36201519, 2022). "A single nucleotide polymorphism (SNP) was discovered to associate with upregulated GSDMB expression and increased susceptibility in asthma." (PMID 35795683, 2022). "Gasdermin A (GSDMA) and gasdermin B (GSDMB) genes are located at chromosome 17, and variants of these genes are confirmed to increase susceptibility to asthma phenotypes in children." (PMID 36201519, 2022). "The association between GSDMA (rs7212938, T/G) and GSDMB (rs7216389, T/C) at locus 17q12-21 and level of IgE immunoglobulin antibody in child and adult Jordanian asthma patients has been tested." (PMID 36201519, 2022). "The association between GSDMB SNP (rs7216389) and susceptibility to adult and childhood asthma among Jordanians has been established in a previous study." (PMID 36201519, 2022). "Markers near the ORMDL3/GSDMB genes on chromosome 17q21 were found strongly associated with childhood-onset asthma, among which the rs7216389 was the most strongly associated with disease." (PMID 36248872, 2022). "A meta-analysis in 2018 found significant association between GSDMB rs7216389 and pediatric asthma risk." (PMID 36248872, 2022). "Cell pyroptosis induced by the GSDMB protein can be eliminated when deleting the entire exon 6 from the splicing variant rs11078928 of the GSDMB gene to reduce the risk of asthma." (PMID 35967302, 2022). "The increased level of GSDMB is found in asthmatics, and the upregulated expression of GSDMB in BECs increases the susceptibility to asthma." (PMID 35819638, 2022). "In a previous study of our research group, it has been reported that genes in 17q12-21 proximal, core and distal regions are associated with asthma, the core region containing the GSDMB gene has been associated with early onset of asthma." (PMID 36201519, 2022). "These were in loci previously associated with asthma exacerbations (GSDMB, RAD50, HLA‐DQB1, ADAM33, VDR, and CDHR3) or moderate‐to‐severe asthma (IKZF3, TSLP, MUC5AC, C11orf30, SMAD3, and WDR36)." (PMID 35754128, 2022). "Positive as well as negative correlations have been observed between rs7216389 of GSDMB and asthma; a meta-analysis found moderate evidence of a correlation between GSDMB rs7216389 variants and asthma." (PMID 34858408, 2021). "Single nucleotide polymorphisms (SNPs) in the GSDMB gene were associated with increased risks of asthma, Crohn’s disease, inflammatory bowel disease, and ulcerative colitis." (PMID 33406603, 2021). "Analogous to GSDMA, GSDMB is also linked to childhood‐onset asthma, while GSDMB (rs9303277) in CD4+ T cells is an SSc‐associated susceptibility locus." (PMID 34459122, 2021). "Several studies have shown that genetic variation in GSDMB is associated with asthma susceptibility and asthma-related phenotypes, such as IgE11 and a change in FEV1 in response to albuterol." (PMID 34858408, 2021). "The SNPrs11078928, which prevents the splicing of exon 6, and thus abolishes the expression of GSDMB isoform 3, was associated with decreased asthma risk, implying that caspase-1-induced, GSDMB-mediated pyroptosis perhaps plays a role in asthma pathogenesis." (PMID 33406603, 2021). "At 17q12-q21, the expression of GSDMB (per SD OR: 1.11, 95% CI: 1.09–1.14, PMR_Corr = 2.14E−13) was positively associated with the risk of asthma." (PMID 34103634, 2021). "Previously, a series of genome‐wide association studies (GWAS) indicated that GSDMA and GSDMB polymorphisms are associated with asthma." (PMID 34590363, 2021).